AIM2 (absent in melanoma 2)
Diseases named in the same sentence as AIM2 in open-access papers (continued):
Sharing a sentence is not in itself a finding about the gene and the disease.
tumor (continued). "Notably, AIM2 expression was an increase in spatial heterogeneity within GBM samples, with strong expression in tumor cores associated with reduced cell proliferation." (PMID 40386782, 2025). "The reduced levels of AIM2 suggest a potential tumor suppressor function in these cancers." (PMID 39744568, 2025). "Another aspect of the AIM2 inflammasome which needs attention is that it could be activated by radiotherapy, through which its anti-tumor effects are based on direct DNA damage through radiation and indirect DNA damage through ROS, resulting in apoptosis." (PMID 40002808, 2025). "In a recent study it was found that Chimeric Antigen Receptor T cell (CAR-T) treatment led to the activation of AIM2 in macrophages and the ensuing release of IL-1β both by inducing the α1- adrenergic receptor (α1-AR)-mediated adrenergic signaling and by releasing tumor cell DNA." (PMID 40002808, 2025). "The knockdown of AIM2 in GC cells leads to increased cellular proliferation and migration, whereas its overexpression results in the opposite effects, highlighting its potential as a tumor suppressor in GC." (PMID 40386782, 2025). "Therefore, AIM2 can act as a tumour promoter or tumour suppressor due to differences in tissue-specific signalling, the nature of DNA damage, and variations in the tumour microenvironment." (PMID 41440367, 2025). "Furthermore, diminished AIM2 expression has been strongly linked to elevated serum alpha-fetoprotein (AFP) levels, vascular infiltration, poor tumor differentiation, incomplete tumor encapsulation, and decreased postoperative survival." (PMID 39744568, 2025). "In addition to its direct effects on tumor cells, AIM2’s role in regulating immune responses is of particular interest." (PMID 40386782, 2025). "However, in colorectal cancer and prostate cancer, AIM2 acted as a tumour suppressor by supporting genomic stability via regulating DNA-PK (repairs breaks in dsDNA) and PI3K/Akt pathways (promotes proliferation and survival)." (PMID 41440367, 2025). "In summary, AIM2 functions as a critical regulator in cancer pathogenesis, demonstrating a range of roles across different cancer types, tumor microenvironments, and stages of disease progression, both in inflammasome-dependent and inflammasome-independent contexts." (PMID 39744568, 2025). "In an in vitro study, knocking down AIM2 in HCC cells enhanced cell migration, the formation of cell pseudopodium, wound healing, and led to the activation of epithelial–mesenchymal transition (EMT) tumor metastasis, whereas the reintroduction of AIM2 attenuated these effects." (PMID 40002808, 2025). "This suppression of EMT is mediated through the Akt signaling pathway and the inflammasome pathway, indicating that AIM2 may exert its anti-tumor effects by modulating critical signaling cascades involved in cancer cell behavior." (PMID 40386782, 2025). "The pharmacological inhibition of Akt reduced the tumor load in AIM2 knockout mice, suggesting that Akt inhibitors could be used to treat AIM2-deficient human cancers." (PMID 40002808, 2025). "Nevertheless, AIM2 may also function as a pro-tumorigenic gene, facilitating tumor progression through both inflammasome-dependent and -independent signaling pathways." (PMID 39600708, 2024). "In OSCC, the increased levels of AIM2 have been correlated with tumor growth and lymph node metastasis; however, the molecular mechanism remains largely unknown." (PMID 38166970, 2024). "In the in vivo model, overexpression of AIM2 led to the inhibition of HCC tumor growth." (PMID 39222064, 2024). "Additionally, we will explore the autophagy pathway and use in vivo models to assess the impact of AIM2 overexpression on tumor growth." (PMID 39222064, 2024). "The occurrence of this tumor cell pyroptosis may be related to AIM2's regulation of the mTOR‐S6K1 pathway." (PMID 39222064, 2024). "Similarly, mouse DCs treated with AIM2 siRNA in vivo and human DCs in vitro exhibit potent anti-tumor immune responses." (PMID 39076969, 2024).
tumor (continued). "In CRC, AIM2 expression is reduced, and its role as tumor suppressor has been documented." (PMID 39684769, 2024). "AIM2 suppresses tumor growth and metastasis by activating immune cells, such as macrophages." (PMID 39222064, 2024). "Additionally, activation of AIM2 in plasmacytoid DCs induces Ca2+ release, triggering calpain activation and IL-1α release, thereby promoting tumor cell proliferation in the lung." (PMID 39076969, 2024). "Consequently, AIM2 upregulation likely reprograms the tumor immune microenvironment towards an immune-inflamed condition characterized by increased IFNγ signaling and PD-L1 expression and is reported to be more responsive to ICI treatment." (PMID 38166970, 2024). "AIM2 plays a crucial role in the development of various tumours." (PMID 38103146, 2024). "However, AIM2 has also been shown to exhibit important protective roles in several physiological and pathological processes such as tumor immune surveillance and neurodevelopment." (PMID 39450183, 2024). "Finally, the effect of AIM2 overexpression on HCC was further evaluated using a subcutaneous tumor model in nude mice." (PMID 39222064, 2024). "In particular, we explored the impact of AIM2 on tumor cell apoptosis and proliferation." (PMID 37932362, 2023). "However, cGAS and AIM2 have been found to respond to pathogen-derived DNA, self-DNA, and tumor-derived DNA." (PMID 37046775, 2023). "Although potential anti-tumor effects of glycyrrhizin, andrographolide, and methylene blue would be evaluated in colon cancer, breast cancer, and liver cancer during clinical trials, specific AIM2 inhibitors are in need." (PMID 36932407, 2023). "Moreover, IL‐1 and IL‐18 production needed AIM2, which enhanced Treg accumulation and tumor progression in vivo." (PMID 37752941, 2023). "We found that tumor samples expressed higher levels of AIM2 compared to normal samples." (PMID 37932362, 2023). "In particular, the AIM2 inflammasome has been reported to be an important tumor regulator with inflammasome-dependent and independent roles in cancer but its exact role remains unclear." (PMID 37449203, 2023). "Whether AIM2 promotes tumor progression through some unknown mechanisms should be further elucidated." (PMID 36932407, 2023). "In addition, A549 tumor CM significantly enhanced the cleavage and maturation of inflammasome components caspase-1 and IL-1β and upregulated AIM2." (PMID 37449203, 2023). "It's plausible that AIM2 plays a significant role in tumor immunity." (PMID 37932362, 2023). "This shows that macrophage AIM2 is important for IL-1β secretion in response to tumor CM." (PMID 37449203, 2023). "Additionally, TAM-derived AIM2 is able to reverse M2-like TAMs into M1-like TAMs that possess anti-tumor activities." (PMID 36932407, 2023). "The AIM2 expression was correlated with survival time tumor grade and stage." (PMID 36923928, 2023). "This provides new insights into the role of AIM2 in tumor research." (PMID 36923928, 2023). "Moreover, AIM2 is recruited to the phagosomes through Fcγ receptor signaling and activated by sensing the phagocytosed tumor DNAs through the disrupted phagosome membrane." (PMID 37046775, 2023). "Our results may be related to the anti-tumor effects of AIM2, as the both 2× and 4× internal exposures resulted in high score levels for mitosis and pyroptosis, with prominent crypt shortening and crypt distortion at day 3 continued to 8 months." (PMID 37491560, 2023). "Moreover, 17 CRNGs were upregulated in tumor tissues, while only AIM2, AXL, and TLRL4 were downregulated." (PMID 37287752, 2023). "The crucial function of AIM2 in tumour and innate immune response is well established." (PMID 35343082, 2022). "Collectively, our data indicate that activation of AIM2 inflammasome could improve the curative effect of BCG by increasing CD11b+ cells infiltration in the tumor microenvironment to achieve antitumor effects." (PMID 36386141, 2022).
tumor (continued). "The strong correlation of AIM2 inflammasomes with several genes suggested that AIM2 inflammasomes may be a new target for tumor therapy." (PMID 36248785, 2022). "Once the AIM2 inflammasome is activated by cellular stress or nucleic acid fragments released by dead cells, tumor cells release inflammatory cytokines and recruit CD11b+ neutrophils to inhibit tumor growth." (PMID 36386141, 2022). "In conclusion, GSDMD, GSDMB, and AIM2 are all promising new targets in cancer therapy, which may be involved in the death mechanism of tumor cell therapy through pyroptosis." (PMID 36569221, 2022). "For instance, AIM2 contributes to tumor suppression and development." (PMID 35734577, 2022). "A similar finding was observed that assessing the pyroptosis patterns could inform the tumor status and guide immunotherapy strategies by investigating the response of AIM2 to immunotherapy in ccRCC." (PMID 36248876, 2022). "AIM2 plays an antitumor role in tumor diseases independently of the inflammasome activation." (PMID 36359370, 2022). "AIM2 inflammasomes may be a new target for future tumor therapy It is likely involved in tumor development, and its high expression may serve as a predictor of tumor immunotherapy efficacy." (PMID 36248785, 2022). "Therefore, AIM2 inflammasomes was associated with increasing TMB, suggesting that AIM2 inflammasomes can be used to predict the curative effect of tumor immunotherapy." (PMID 36248785, 2022). "Multiple inflammasomes, including NLRP3, NLRC4, NLRP1, and AIM2, may inhibit tumor initiation by influencing innate and adaptive immunity, apoptosis, and differentiation." (PMID 36437954, 2022). "Therefore, that the role of AIM2 inflammasomes is variable, and AIM2 inflammasomes are a double-edged sword against cancer in that they can prevent or promote tumor development in depending on cancer type." (PMID 36248785, 2022). "AIM2 is also reported to be a tumor suppressor or oncogene in inflammasome-independent manner." (PMID 36386141, 2022). "Therefore, AIM2 not only can induce pyroptosis but also affect the status of TME to modulate tumor behaviors." (PMID 35281845, 2022). "Surprisingly, the AIM2 inflammasome is highly expressed in pDCs, which enhances calcium efflux and reactive oxygen species (ROS) release from mitochondria, resulting in calpain activation and IL‐1α release, thereby promoting tumor proliferation." (PMID 34014039, 2021). "Additionally, AIM2 expression was further reduced in GC tissues with tumor-node-metastasis (TNM) stage III–IV (P < 0.001) and with tumor size ≥ 5 cm (P < 0.01), compared to TNM stage I–II and tumor size < 5 cm, respectively." (PMID 33859277, 2021). "Besides, in tumor tissues, the expression level of AIM2 was significantly higher than that in normal renal tissues." (PMID 35070978, 2021). "In addition, our research showed that AIM2 was highly expressed in ccRCC and promoted tumor development through immune activation pathways." (PMID 35070978, 2021). "Additionally, overexpression of AIM2 significantly inhibits tumor growth and metastasis in BRAF-mutant CRC in vivo, which was further confirmed in BRAF-mutant CRC PDOs." (PMID 33842454, 2021). "Thus, AIM2 inflammasome in macrophages can initiate the innate immune response, and participate in escape adaptive immune response for tumor cells." (PMID 34014039, 2021). "Although the molecular mechanism of AIM2 involved in regulating the biological behavior of tumor cells is complex, AIM2 has been speculated to exert an antitumor effect, mainly by activating the inflammasomes in GC patients." (PMID 34680930, 2021). "Moreover, clinical analyses have also revealed that AIM2 expression is significantly correlated to tumor size, LNM and TNM stage." (PMID 33859277, 2021). "In addition, our loss-of-function and gain-of-function experiments suggest that AIM2 inhibits GC cell proliferation and migration, which suggests that AIM2 plays a tumor-suppressive role in GC." (PMID 33859277, 2021).
tumor (continued). "In this study, we first investigated AIM2 expression level in BRAF-mutant CRC tumor tissues." (PMID 33842454, 2021). "Additionally, knockdown of AIM2 in these cells leads to an inhibition of tumor cell growth and migration, suggesting that AIM2 functions as an oncogene." (PMID 33859277, 2021). "Interestingly, in our study, AIM2 seemed to be a cancer-promoting gene, as it was upregulated threefold in tumour tissues; however, it also contributed to prolonged patient survival because it was enriched in the low-risk group." (PMID 33828074, 2021). "Furthermore, we also found that restoration of AIM2 expression significantly inhibited tumor pulmonary metastasis, showing the reduced tumor burden in the lung and the number of metastatic foci." (PMID 33842454, 2021). "In addition to elucidating the clustering results of 32 PRs, we explored the relationship between the PRs and TME cell-infiltrating characteristics and focused on the specific role of AIM2 in regulating the tumor immunity." (PMID 34680930, 2021). "Interestingly, COPD adenocarcinoma patients who had lower levels of AIM2 in the tumor tissue had higher survival rate (6.3 years) compared to patients who had higher levels of AIM2 in the tumor tissue (2.7 years) (red vs black line)." (PMID 34084280, 2021). "Besides, we explored that AIM2-silenced SCC-7 cells inhibited subcutaneous tumor growth in immune-competent mice, which implied a direct effect of AIM2 on cancer epithelial cell growth." (PMID 33391539, 2021). "Similarly, AIM2‐adjuvant vaccines exhibit antitumor therapeutic efficacy by heightening tumor‐specific CD8+ T cell immunity." (PMID 34014039, 2021). "Moreover, we confirmed the antitumor effect of AIM2 in BRAF-mutant CRC cell-derived tumor xenograft (CDX) models as well as patient-derived organoids (PDOs)." (PMID 33842454, 2021). "Therefore, our data suggests that AIM2 is a novel tumor suppressor, and highlights the possible role of AIM2 as a therapeutic target for GC treatment." (PMID 33859277, 2021). "Next, we investigated the clinical relevance of AIM2 expression in 86 CRC tumor tissues." (PMID 33291082, 2020). "Therefore, through this inflammasome-independent mechanism, AIM2 was able to reduce Akt activation and tumor development in a mouse model of CRC." (PMID 32906750, 2020). "Subsequently, this indicates that AIM2 activation plays an important role in virotherapy-induced growth inhibition by secretion of inflammatory cytokines, which attract and activate immune cells against tumor cells." (PMID 32225009, 2020). "On the other hand, excessive AIM2 expression suppressed tumor growth in breast carcinoma." (PMID 33291082, 2020). "In addition to its role in inflammasome activation, AIM2 has recently been described as both a oncogene and tumor suppressor in different types of cancers." (PMID 33291082, 2020). "Mechanically, the tumor-suppressive functions of AIM2 in CRC were mediated through its participation in repressing the AKT/mTOR pathway, and the inactivated AKT/mTOR failed to increase Gli1 protein expression, resulting in the inhibition of cell proliferation and migration." (PMID 33291082, 2020). "Additionally, Ad‐CAIXpromotor‐AIM2 displayed potent anti‐tumour activity in OSRC‐2‐xenograft model or lung metastasis model." (PMID 32725966, 2020). "In this study, we discovered a reduced expression and anti-tumor properties of AIM2 in CRC." (PMID 33291082, 2020). "Results of IHC and Western blots showed a remarkably decreased expression of Gli1 protein in tumors derived from HCT116 cells stably expressing AIM2, suggesting Gli1 may be involved in tumor growth regulated by AIM2 in CRC." (PMID 33291082, 2020). "In HPV-infected CC cells, AIM2 can play a tumor inhibitory role by stimulating pyroptosis." (PMID 31501419, 2019). "Therefore, our study showed that luteolin inhibited tumor growth of A549 and H460 cells in vivo through AIM2 inhibition." (PMID 30833546, 2019).
tumor (continued). "AIM2 is known to play a critical role as a tumor suppressor." (PMID 31205871, 2019). "Absent in melanoma 2 (AIM2) as a tumour suppressor might be used as a potential therapeutic target for RCC treatment." (PMID 30160343, 2018). "Taken together, these data indicated that H1/AIM2 treatment with low toxicity could effectively prevent the aggravation of tumour." (PMID 30160343, 2018). "Accordingly, the volume and weight of tumour were decreased in H1/AIM2‐treated group." (PMID 30160343, 2018). "AIM2 expressing tumor cells were located at the invasive edges of the cSCC tumor." (PMID 28526809, 2017). "AIM2 was initially identified as a tumor suppressor in melanoma." (PMID 28955343, 2017). "Tumor cell-specific cytoplasmic and perinuclear AIM2 expression was noted in all cSCCs." (PMID 28526809, 2017). "Besides these experimental data, clinical investigation also supported the tumor suppressor role of AIM2 in HCC patients." (PMID 27167192, 2016). "Thus, our integrated data from clinical investigation, cellular model and animal model altogether demonstrated the tumor suppressor role of AIM2 in HCC." (PMID 27167192, 2016). "Since ligand requirements for AIM2 inflammasome are quite permissive, we are interested to define whether the anti-tumor effect of AIM2 in HCC cells is mediated by AIM2 inflammasome." (PMID 27167192, 2016). "The authors found that the genetic ablation of AIM2 in mutated KrasG12D LUAD mouse models significantly reduced tumor growth, and that AIM2 expression was required in both hematopoietic and non-hematopoietic cellular compartments for Kras G12D-driven LUAD establishment." (PMID 40002808, 2025). "So far, tumor-derived or chemotherapy-induced ICD with an ensuing release of alarmins is able to activate the NLRP3 inflammasome due to the alteration of the mitochondrial homeostasis or the AIM2 inflammasome after the recognition of double-stranded DNA (dsDNA) released by dying cells." (PMID 39857785, 2025). "However, it was revealed that the AIM2 inflammasome can suppress HCC in that its levels were significantly decreased in liver cancer tissues, and the loss of its expression was significantly correlated with more advanced tumor progression." (PMID 40002808, 2025). "Additionally, AIM2 might influence the tumor microenvironment by affecting immune cell infiltration and function." (PMID 40386782, 2025). "Additionally, Aim2-/- mice demonstrated accelerated growth of colon stem cells, enhanced stem cell activity in Prom1+ cells following abnormal Wnt activation, and a greater propensity for tumor formation." (PMID 39744568, 2025). "Additionally, Aim2-/-/ApcMin/+ mice exhibited increased tumor burdens compared to ApcMin/+ mice." (PMID 39744568, 2025). "However, in a mouse model of BLCA overexpressing AIM2, tissue samples were more highly infiltrated by CD11b+ cells, suggesting that DNA fragments released by dead and tumor cells could lead to immune cell infiltration via AIM2." (PMID 40002808, 2025). "Additionally, AIM2 promotes the polarization shift from anti‐inflammatory M2 TAMs towards pro‐inflammatory M1 phenotype through inflammasome signaling activation, thereby enhancing tumor‐killing activity." (PMID 39222064, 2024). "Although further experiments are still needed to explore the role of AIM2 in promoting the reprogramming of tumor immune microenvironment, our results suggest that ICIs could be an effective therapeutic strategy to combat the refractory OSCC with AIM2 upregulation." (PMID 38166970, 2024). "Notably, we propose P38MAPK as a tumor suppressor regulating the effects of AIM2 on CRC." (PMID 38186575, 2023). "The complex role of AIM2 in the tumor microenvironment may be more complicated through its inhibition of several signaling pathways including AKT as well as STING-type 1 interferon signaling (7b) Most importantly, how AIM2 gets activated in cancer remains unknown." (PMID 37449203, 2023).